KEAP1 (kelch like ECH associated protein 1)
Diseases named in the same sentence as KEAP1 in open-access papers (continued):
Sharing a sentence is not in itself a finding about the gene and the disease.
tumor (continued). "Mutations in FAT1 and KEAP1 generated several complex tumor antigens and higher TMB, but as the expression of many immune-related genes was significantly lower, it may lead to immune escape or poor efficacy of ICBs." (PMID 33808631, 2021). "Furthermore, it has been reported that the deletion of Exon2 in NRF2, which reduces interaction with KEAP1, causes tumor development in lung and liver cancer." (PMID 32751080, 2020). "KEAP1 mutations also occur in HCC tumours and when mapped, are found throughout the gene." (PMID 33276631, 2020). "Tumor cells often increase their antioxidant potentials by activating the transcription factor Nrf2 following disruption with its binding partner Kelch-like ECH-associated protein 1 (Keap1)." (PMID 33233630, 2020). "However, it will be important to further validate that these KEAP1 mutations are enriched in tumor‐initiating cells or CSCs." (PMID 33173725, 2020). "Here, the sustained activation of NRF2 due to KEAP1 LOF mutation was seen to promote tumor growth and upregulate the expression of PPP genes, including G6PD, TKT and PGD, through the epigenetic inhibition of miR-1 and miR-206, two repressors of metabolic gene induction." (PMID 32443774, 2020). "Because deregulation of the Nrf2 signaling is linked to chemo-resistance in a variety of tumor types, the reversal of KEAP1 methylation or NRF2 demethylation could be a novel strategy to increase anticancer drug sensitivity." (PMID 31022969, 2019). "This concept has been previously established in patients with non-small cell lung carcinoma (a tumor with a much higher rate of KEAP1 somatic mutations), where the presence of such mutations is associated with decreased disease-free survival and decreased overall survival." (PMID 31428048, 2019). "In PTC, such Nrf2-activating KEAP1 mutations have been associated with tumor aggressiveness." (PMID 31428048, 2019). "The observed lack of macrophage infiltration with pro-tumorigeneic characteristics in KEAP1-mutant tumors may suggest that KEAP1-deficient tumors hijack alternative tumor-promoting mechanisms to drive and sustain tumor cell growth." (PMID 31519898, 2019). "Furthermore, Keap1 loss reprogrammed the metabolic wiring of oncogenic KrasG12D tumor cells by hijacking the pentose phosphate pathway (PPP)." (PMID 31519898, 2019). "Moreover, KEAP1 promoter silencing by methylation was also predictive of a lower risk of tumor relapse in patients treated with sequential therapy of anthracyclines and cyclophosphamide followed by taxanes." (PMID 29643973, 2018). "In addition to this, authors analyzed 481 ccRCC TCGA data sets independently and showed that KEAP1 methylation is associated with tumor staging, grading and overall survival of patients." (PMID 28812986, 2017). "For example, ME1 expression is known to be regulated by Nrf2, and tumours with mutated Keap1 or Nrf2 genes could be dependent on ME1 and thus be sensitive to ME1 inhibition." (PMID 28481367, 2017). "As such, we next investigated whether WDR23 expression is altered in tumor samples harboring KEAP1 mutations and vice versa." (PMID 28453520, 2017). "The Keap1/Nrf2 pathway is a master regulator of the cellular redox state through the induction of several antioxidant defence genes implicated in chemotherapeutic drugs resistance of tumor cells." (PMID 28061437, 2017). "Nrf2, Keap1, and Notch1 rank among the first frequently mutated genes in tumors and were deemed to be significant both in the combined sets of tumors and in individual tumor types." (PMID 27847554, 2016).
tumor (continued). "Along with KEAP1 mutations, the expression levels of two Nrf2 downstream transcripts expressions, Ho-1 and Nqo1, were found significantly associated with tumor invasiveness and patients survival in NSCLC advanced stage." (PMID 27847554, 2016). "Therefore, genetic induction of NRF2 by loss of KEAP1 function appears to have a different effect than AIM-mediated activation of NRF2 via KEAP1 inhibition on tumor growth." (PMID 26301506, 2015). "The apparent survival advantage provided to some tumor cells by loss of functional KEAP1 raises the question of whether pharmacological inhibition of KEAP1 could promote tumor growth." (PMID 26301506, 2015). "Taken together, the results from this study demonstrate that NRF2 induction by AIMs does not increase cellular proliferation or survival and that the downstream effects of pharmacological KEAP1 inhibition by AIMs are distinct from those that result from the loss of functional KEAP1 in tumor cells." (PMID 26301506, 2015). "To determine whether loss of functional KEAP1 is also correlated with increased proliferation in human tumor cells, we used the sulforhodamine B (SRB) assay to assess the growth of each of the 20 cell lines over a 72-hour period." (PMID 26301506, 2015). "Moreover, somatic heterozygous loss of function mutations in Keap1 were also identified in various tumor tissues." (PMID 25014534, 2014). "Furthermore, oncogenic KRAS might exacerbate oxidative stress and anabolic metabolism, potentially synergizing with KEAP1/STK11 co-mutations to drive tumor aggressiveness." (PMID 41541668, 2026). "Aberrant activation of NRF2 via KEAP1 mutation is also associated with poor clinicopathological outcomes, including low-response rate to platinum-based chemotherapy, increased metastasis (long distance, lymph node, and tumor node), poor overall survival rate, and poor progression-free survival." (PMID 41573641, 2025). "Additionally, tumor-associated gene pathways including glutathione metabolism, chemical carcinogenesis, metabolism of xenobiotics by cytochrome P450 and cell adhesion molecules were significantly associated with KEAP1 mutation in LUADs." (PMID 38962454, 2024). "Among the significantly upregulated proteins in JunBlo microglia cells we found the proteins: Rheb, synaptophysin, and KEAP1, which are reported to be associated with inflammatory response, and therefore may facilitate tumor-restraining properties in JunBlo microglia." (PMID 37894348, 2023). "However, patients with Keap1 mutations developed tumor regrowth in the lung." (PMID 35945195, 2022). "Conceivably, systemic changes in redox signalling with exercise, could activate redox-sensitive antioxidant genes within the tumour (possibly through kelch-like ECH-associated protein 1-nuclear factor (erythroid-derived 2)-like 2 (Keap-Nrf2) and PGC-1α) to attenuate oxidative damage." (PMID 35394236, 2022). "Taken together, the results above highlight the possibility that KEAP1‐wild type tumors are associated with higher tumor immunity and, therefore, may be sensitive to immunotherapy, providing a new treatment modality and biomarker for those LUADs with KEAP1‐wild type." (PMID 34328274, 2021). "Given that chemokine network activity plays an important role in regulating the tumor immunity, it is assumable that the potential way of KEAP1 mutation impacting the immunity as suggested from the results above, might be likely related to damaging the chemokine network activity in LUADs." (PMID 34328274, 2021). "This further suggested that KEAP1‐mutated LUAD patients may harbor the impaired tumor immunity." (PMID 34328274, 2021). "NRF2 inhibition with ML385 could inhibit the proliferation of tumor cells with KEAP1 mutation." (PMID 32576270, 2020).
tumor (continued). "Moreover, NRF2 promotes GSH synthesis also from a metabolic point of view as demonstrated in tumours bearing mutated Kelch-like ECH-associated protein 1 (KEAP1), a negative regulator of NRF2 stability, in which glutamine-derived glutamate is used for GSH production at the expense of the Krebs cycle." (PMID 31426306, 2019). "Considering these findings, we could infer that tumor with KEAP1 or NFE2L2 mutation would have a higher level of oxidative stress, which could lead to the destruction of immune cells including CD8+ TILs and increased DNA damage level, resulting in the increase of somatic mutations of tumor cells." (PMID 31299995, 2019). "Consistently, immune infiltration analysis revealed striking reductions in various immune cells in KEAP1-, STK11- or CDKN2A-mutated tumors, characterizing the suppressive tumor immune microenvironment (TIME)." (PMID 41491583, 2026). "Clinical samples confirmed elevated miR-941 and a molecular signature consistent with Keap1 downregulation and Nrf2 activation in resistant tumours." (PMID 42298893, 2026). "Taken together, baseline KEAP1, STK11, and CDKN2A mutations detected by liquid biopsy indicate a poor prognosis, which was also confirmed by tumor tissue-based mutation sequencing data." (PMID 41491583, 2026). "In this study, we found LKB1 mutations frequently co-occur with mutations in Kelch-like ECH-associated-protein 1 (KEAP1), another key tumour suppressor regulating the NRF2-mediated antioxidant response." (PMID 42157939, 2026). "WES/WGS and RNA-seq confirmed the poor prognostic effect of KEAP1, STK11, and CDKN2A mutations, which were characterized by the suppressive tumor microenvironment and attenuated humoral immunity." (PMID 41491583, 2026). "Gain-of-function mutations in NRF2 disrupt its negative regulation by Kelch-like ECH-associated protein 1 (KEAP1), resulting in sustained NRF2 signaling that promotes tumor growth and resistance to chemotherapy and radiation." (PMID 42122150, 2026). "The poor prognostic value of KEAP1, STK11, and CDKN2A mutations was further validated in the tumor tissue WES/WGS data." (PMID 41491583, 2026). "Co‐occurring mutations with smoking‐related canonical mutations, such as KRAS, STK11, and KEAP1, are common in patients with SMARCA4 mutations, and up to 44% of these patients exhibit a smoking‐related co‐mutation signature and a high tumor mutational burden." (PMID 41577374, 2026). "Lower and higher magnification images of HE staining of tumors showed that tumor area and stroma area are observed similarly in both KEAP1-KO and DKO tumor tissues." (PMID 41035689, 2025). "In a murine model of urea-induced lung cancer, Keap1 knockout mice exhibited rapid urinary urea excretion and reduced tumor incidence, consistent with Nrf2-induced drug detoxification." (PMID 40242036, 2025). "Nrf2/Keap1 is crucial for redox balance and protecting cells from oxidative stress, making it a key factor for tumor survival." (PMID 40867215, 2025). "Survival benefits were observed across PD-L1 strata, tumor histologies, and high-risk molecular subgroups such as KRAS, STK11, and KEAP1, and in patients with brain metastases." (PMID 41479494, 2025).
tumor (continued). "KDR promotes tumor angiogenesis, while the hypermethylation of the Keap1 promoter reduces KEAP1 expression, contributing to tumor progression." (PMID 40136480, 2025). "In HCC, ADAR1 plays a predominantly oncogenic role by maintaining redox homeostasis through modulation of the Keap1/Nrf2 pathway, enabling tumor cells to survive oxidative stress." (PMID 40852728, 2025). "Higher magnification images clearly showed that high-level NQO1 expression was observed in tumor areas (shown by T) of the KEAP1-KO tumor tissues, because of the strong NRF2 activation." (PMID 41035689, 2025). "Tumor latency was identical between genotypes (WT 127±25; KO 123.4±31 days), but once palpable, lesions in conditional Keap1 KO hosts expanded significantly faster than those in WT controls (genotype×day p=0.0003)." (PMID 41176316, 2025). "This study provides the first direct evidence of tumor progression from PTC to SCC, likely created by sequential loss‐of‐function of tumor suppressor genes (KEAP1 and STK11), in humans." (PMID 40600748, 2025). "To examine the tumor immune microenvironment of WT and KEAP1-KO tumors, we collected tumor tissues and performed flow cytometry after tumor cell dissociation, red blood cell lysis, and debris removal." (PMID 41035689, 2025). "In contrast, among patients with both STK11 and KEAP1 wild-type tumours, low TMB and alterations in the ERBB2 pathway were detected in 2/3 of cases." (PMID 40650126, 2025). "Intriguingly, this CD45-positive immune cell infiltrations were severely abrogated in the stroma areas of KEAP1-KO tumor tissues." (PMID 41035689, 2025). "The most robust effort to date, an analysis of over 1,000 tumors across 10 tumor subtypes using CPTAC proteogenomics data, identified that mutations in Keap1 and NRF2 were associated with diminished IFNγ and CD8 T cells." (PMID 40946102, 2025). "Numerous molecules that inhibit tumor formation or growth, affect mitochondria, and interact with the Nrf2/Keap1 pathway are currently being developed." (PMID 41304943, 2025). "Recent studies highlight the potential of combining glutaminase inhibitors with ICIs to exploit metabolic vulnerabilities in KEAP1-mutant tumours." (PMID 40277912, 2025). "The immunomodulatory and tumor-reducing effects of CDDO-Me in the KEAP1 KO group were of particular interest, as patients harboring these mutations present with more resistant disease and are uniquely difficult to treat." (PMID 41462606, 2025). "T-cells exposed to supernatants from spheroids hosting macrophages showed markedly reduced tumor cell killing, with the effect more pronounced for spheroids containing Keap1 KO macrophages." (PMID 41176316, 2025). "Lower magnification images of Hematoxylin-Eosin (HE) stained tumors exhibited that tumor area (shown by T) and stroma area (shown by S) are observed similarly in both WT and KEAP1-KO tumor tissues." (PMID 41035689, 2025). "Omaveloxolone similarly decreased tumor size and weight by 85.4% and 70.7%, respectively, limiting tumor growth to approximately 200 mm3 after 10 days of treatment in KEAP1 KO tumors." (PMID 41462606, 2025). "Surprisingly, in vivo studies show higher expression of PD-L1 in CD8+T cells in KEAP1null/KRASG12D-mutant tumours as compared to KEAP1WT/KRASG12C tumours, suggesting the role of KEAP1 in regulating the immune response and immunosuppression." (PMID 40647497, 2025).
tumor (continued). "We subsequently investigated the influence of KEAP1/STK11 mutations on established biomarkers of immunotherapeutic response, such as PD-L1 expression and tumor mutation burden (TMB)." (PMID 41378285, 2025). "In contrast, co-occurring STK11/KEAP1 mutations, probably due to the STK11 impact on “cold” tumour microenvironment, lead to lower levels of PD-L1 expression and decreased response to immunotherapy." (PMID 40650126, 2025). "Among patients with both STK11 and KEAP1 wild-type tumours, a low TMB and alterations in the ERBB2 pathway were detected in 66.7% of cases." (PMID 40650126, 2025). "The Nrf2/Keap1 signaling pathway is essential for sustaining cellular redox homeostasis and for the regulation of tumor development via the modulation of oxidative stress responses." (PMID 40867215, 2025). "As a proportion of total MDSCs, KEAP1 KO tumors had an increased proportion of tumor-promoting PMN-MDSC compared to WT." (PMID 41462606, 2025). "Spatial transcriptomics, single-cell RNA sequencing, and Keap1-deficient mice showed that the latter are NRF2-imprinted “stress-TAMs”, with immunosuppressive and tumor-promoting activity." (PMID 41176316, 2025). "In these genes, the hypermethylation of the Keap1 promoter leads to decreased KEAP1 mRNA and protein expression, contributing to tumor progression." (PMID 40136480, 2025). "Specifically, our objectives were to investigate how triterpenoids modulate macrophage phenotypes and to evaluate triterpenoid efficacy in reducing the tumor burden in KEAP1-mutant mouse models." (PMID 41462606, 2025). "This approach targets the metabolic vulnerabilities of KEAP1-mutant tumours, potentially enhancing the response to immunotherapy." (PMID 40277912, 2025). "It has been reported that KEAP1 and STK11 variants are associated with poorer responses to ICI, especially with lower PD-L1 scores of the tumor." (PMID 40869405, 2025). "WES analysis of 60 pRCC specimens revealed six tumours (10%) with mutations in the four key genes, NFE2L2, KEAP1, CUL3 and BACH1, of the NRF2‐ARE pathway." (PMID 39707614, 2025). "Its downregulation is correlated with poor survival outcomes in high-risk patients characterized by elevated tumor mutational burden (TMB) and KEAP1 mutation enrichment." (PMID 41170198, 2025). "Clinically, KRAS-mutant tumors with STK11/KEAP1 inactivation are known to be less responsive to immune checkpoint inhibitors and often exhibit a “cold” tumor immune microenvironment (low PD-L1, Programmed Death-Ligand 1, with low T-cell infiltration)." (PMID 40723270, 2025). "Constitutive activation of KEAP1/NRF2 reprograms tumor metabolism toward glutaminolysis and PPP flux, generating NADPH and GSH to buffer oxidative stress and promote invasive growth." (PMID 41470226, 2025). "Given previous reports linking KEAP1/STK11 co-mutations to an immune cold phenotype in LUAD, we sought to explore the relationship between KYNU expression and tumor immune infiltration." (PMID 40427178, 2025). "It is important to note that analysing fast disease progression cases in our research, both patients with STK11 and KEAP1 wild-type tumours had low TMB and harboured ERBB2 alterations (amplification and co-occurring alteration)." (PMID 40650126, 2025). "STK11, KEAP1, and SMARCA4 are tumor suppressors in lung tissue and mutations in those genes correlate with significantly worse outcomes for patients with NSCLC, particularly after ICI therapy." (PMID 41387924, 2025). "Another review summarizes the relationships between the Keap1-Nrf2 signaling pathway and tumor development." (PMID 41304943, 2025).